SLC35F4 (solute carrier family 35 member F4)
Description:
Mediates choline transport, although the underlying transport mechanism remains to be elucidated.
Synonyms: C14orf36; FLJ37712; c14_5373
Tractability: Antibody: UniProt predicts a signal peptide or a membrane-spanning region. PROTAC: ubiquitination databases record sites on it.
Gene: Protein-coding gene on chromosome 14 (57,563,920 to 57,982,194, reverse strand). Ensembl gene ENSG00000151812.
Subcellular location: Membrane
Gene Ontology:
Molecular function: choline transmembrane transporter activity
Biological process: choline transport
Cellular component: membrane
Genetic constraint (gnomAD): Loss-of-function variants: 24 observed, 41.95 expected, observed/expected ratio (o/e) 0.57, 90% interval 0.41 to 0.81. The upper end of that interval is the gene's LOEUF score, 0.81, which puts it in group 3 of 6, group 1 being the genes least tolerant of losing a copy. Missense variants: 562 observed, 598.33 expected, observed/expected ratio (o/e) 0.94, 90% interval 0.88 to 1.01. Synonymous variants: 238 observed, 224.73 expected, observed/expected ratio (o/e) 1.06, 90% interval 0.95 to 1.18.
Homologues: Orthologues: macaque SLC35F4 (99% identical), pig SLC35F4 (97% identical), dog SLC35F4 (97% identical), rabbit SLC35F4 (96% identical), mouse Slc35f4 (95% identical), rat Slc35f4 (95% identical), chimpanzee SLC35F4 (94% identical), guinea pig SLC35F4 (87% identical), tropical clawed frog slc35f4 (76% identical), zebrafish slc35f4 (65% identical), Drosophila melanogaster CG42322 (28% identical), Caenorhabditis elegans Y73B6BL.31 (24% identical). Paralogues in human: SLC35F3 (48% identical).
Diseases named in the same sentence as SLC35F4 in open-access papers:
SLC35F4 is named in the same sentence as 3 diseases in open-access papers, as found by Europe PMC text mining. Sharing a sentence is not in itself a finding about the gene and the disease. The quoted sentences say what the papers report.
cancer (1 paper, 2026). A tumor composed of atypical neoplastic, often pleomorphic cells that invade other tissues. "Moreover, other expression analyses revealed decreases in the abundance of SLC35F4 in various tumor types, suggesting that its loss may disrupt cofactor homeostasis or Golgi-associated signaling, thereby influencing metabolic reprogramming or antioxidant responses in cancer cells." (PMID 41516385, 2026).
SLC35F4 also shares sentences with these, for which no sentence is quoted: microcephaly (1 paper); tumor (1).